INS (insulin)
Diseases named in the same sentence as INS in open-access papers (continued):
Sharing a sentence is not in itself a finding about the gene and the disease.
Hyperinsulinemia (continued). "Sex dimorphism in response toFGF21 was reported earlier in obese Ay mice: FGF21 administrationdecreases hyperinsulinemia and hepatic lipid accumulation,increases muscle expression of genes involvedin fatty acid oxidation and insulin signaling only in obeseAy males." (PMID 37469453, 2023). "Moreover, insulin mediates follicular development, promoting the arrest of follicle development in the setting of hyperinsulinemia." (PMID 38004264, 2023). "Regarding the mechanism involved, hyperinsulinemia may decrease UA clearance by the kidneys, because of the effects of insulin on proximal tubular urate transport of the kidney." (PMID 37736731, 2023). "Such a REG3A-mediated mechanism of action most likely promotes induction of gp130-AMPK signaling and thus bypasses the typical impairment of insulin signaling, leading to minimization of the amount of insulin needed to control blood glucose and reduce hyperinsulinemia." (PMID 36918710, 2023). "Competition during hyperinsulinemia may lead to the elevation of Aβ via the competitive inhibitory effect of insulin on IDE." (PMID 37372995, 2023). "Indeed, consistently to our findings, increased adiponectin levels consequently to PTP1B inhibition has been correlated to an amelioration of insulin sensitivity and a resulting decreased hyperinsulinemia and glucose intolerance in various animal models." (PMID 37020593, 2023). "Since insulin induces blood stem cells to differentiate into chondrocytes, hyperinsulinemia may induce cartilage formation and growth, followed by ligament ossification." (PMID 37629454, 2023). "Therefore, metformin’s mechanism of chemoprevention is not thought to be solely attributable to adequate control of blood glucose but also to its ability to reduce hyperinsulinemia and subsequent insulin signaling pathway activity." (PMID 36857596, 2023). "Additionally, in vivo, insulin secretion was greatest in the 129 strain, and response to hyperinsulinemia was intermediate in the C57 strain." (PMID 37960308, 2023). "The hPGH may also have the same diabetogenic effects as pituitary growth hormone, including hyperinsulinemia, decreased glucose uptake and glycogensynthesis triggered by insulin, and a reduction in insulin's capacity to control hepatic gluconeogenesis." (PMID 37814679, 2023). "Here, we find that adipocyte Mboat7 contributes less so to hepatic steatosis and injury than hepatocyte Mboat7 but instead plays a critically important role in regulating local adipose tissue LPI/PI homeostasis, hyperinsulinemia, and systemic insulin sensitivity." (PMID 36806709, 2023). "Therefore, in a state of hyperinsulinemia, insulin binds the IDE leading to Aβ protein accumulation." (PMID 36901787, 2023). "The non-diabetogenic hyperinsulinemia clusters associated with non-increased T2D risk exhibited characteristics indicative of preserved insulin production." (PMID 37790568, 2023). "Insulin dysregulation can be manifested by hyperinsulinemia." (PMID 37628596, 2023). "Several epidemiological and laboratory studies have shown a complex relationship between age and insulin secretion and clearance: while increased insulin secretion and hyperinsulinemia are more prominent in late middle age, decreased insulin secretion is observed in advanced old age." (PMID 38068822, 2023). "Chronic hyperinsulinemia can result in arterial hypertension not only for the elevated levels of ET-1 and the increased sympathetic tone, but also for a documented anti natriuretic effect of insulin." (PMID 38001929, 2023). "Our data indicate that acute insulin stimulation following hyperinsulinemia significantly increases the phosphorylation of IRS1Y608, suggesting that clathrin-mediated mechanisms are prevented due to a lack of molecular engagement with respective players at the internalization site." (PMID 37834116, 2023).
Hyperinsulinemia (continued). "Therefore, in these cases, the compensatory mechanism to keep glucose levels in optimal parameters is to increase insulin secretion in pancreatic cells, resulting in hyperinsulinemia." (PMID 36677012, 2023). "Also, increased levels of TNF-α expression is strongly correlated with hyperinsulinemia and decreased insulin sensitivity." (PMID 37215099, 2023). "By potentiating postprandial insulin secretion and increasing blood insulin levels, there is some concern that pharmacological agonism of the GIPR signaling pathway could increase risk of hyperinsulinemia-driven cancers." (PMID 37250804, 2023). "Moreover, insulin mediates follicular development, promoting the arrest of pre-antral follicle development in the setting of hyperinsulinemia." (PMID 36834549, 2023). "In some of the patients, the nesidioblastosis-related hyperinsulinemia led to a reversal of the diabetic syndrome, and insulin therapy could be discontinued." (PMID 37371827, 2023). "Hyperinsulinism is a medical condition characterized by inappropriately high insulin secretion compared to plasma glucose concentration, leading to a continuous stimulation of hepatic glycogen synthesis and glucose uptake by skeletal muscles and adipose tissue." (PMID 37630734, 2023). "They demonstrated comparable insulin sensitivity between both groups; however, the hyperinsulinism observed in PCOS set both groups apart, and both fasting and glucose-stimulated insulin levels in women with PCOS were strongly influenced by MCRI, which was significantly lower in the PCOS group." (PMID 36834549, 2023). "Specifically, leucine and isoleucine, together with glutamate, are insulin secretagogues, and therefore, their chronic increase, enhancing insulin secretion, could contribute both to hyperinsulinism and, consequently, to pancreatic beta cell insufficiency." (PMID 36984854, 2023). "Hyperglycemia and hyperinsulinemia-mediated inhibition of inositol uptake to the CNS may leave the CNS deprived of inositol thereby inhibiting insulin signaling." (PMID 36038539, 2022). "Maternal obesity is associated with hyperinsulinemia, however maternal insulin does not cross the placenta." (PMID 36329895, 2022). "Additionally, short-term OPP exposure decreased plasma insulin levels in nearly all rodent studies, whereas long-term exposure to either monocrotophos or malathion led to hyperinsulinemia in vivo." (PMID 35156417, 2022). "IR refers to impaired insulin action in glucose uptake, utilization, and other aspects, that is, the biological effect of a certain amount of insulin is lower than the expected normal level, and the body develops compensatory hyperinsulinemia to overcome IR." (PMID 36072812, 2022). "Methionine, the amino acid that showed marked decreases during induced hyperinsulinemia and was significantly less concentrated in the plasma of insulin dysregulated and laminitic horses than in the plasma of obese horses, is an essential proteinogenic amino acid." (PMID 36552500, 2022). "Our clamp study allowed us to evaluate the relationship between total insulin extraction and induced hyperinsulinemia that is typical of prandial insulin levels after GB (~1500 pmol/min), in the absence and presence of meal stimuli, while insulin secretion is maximally suppressed." (PMID 35887007, 2022). "Poor glycemic control can lead to hyperinsulinemia, and insulin may exert mitogenic effects through the insulin-like growth factor 1 (IGF-1) receptor, thereby stimulating cell proliferation and inhibiting apoptosis." (PMID 36387876, 2022). "HFD-fed LKO mice display an increase in basal insulin levels, suggesting that hyperinsulinemia could contribute to the pathophysiology observed." (PMID 35349482, 2022). "Thus, despite hyperinsulinemia, insulin signaling was lower in Cyp7b1−/− mice, suggesting that these mice were insulin-resistant." (PMID 35478959, 2022). "Thus, the changing of receptor affinity for insulin is another property that contributes to hyperinsulinemia." (PMID 35163806, 2022).
Hyperinsulinemia (continued). "PCOS is characterized by hyperinsulinemia, reduced insulin sensitivity, and hyperandrogenism." (PMID 36499573, 2022). "Pancreatic cancer initiates hyperinsulinemia and delays insulin secretion peak, while insulin mediates cancer cell metabolism to maintain PDA survival with proliferation, and insulin also stimulates the formation of a tumor-promoting microenvironment around cancer cells." (PMID 35252207, 2022). "Hyperinsulinemia was ameliorated after SGLT2i treatment, and this insulin-lowering effect might be induced by increased hepatic insulin clearance." (PMID 35115614, 2022). "In addition, IR impedes glucose removal, giving rise to hyperinsulinemia, and IR is a widespread condition affecting numerous organs and insulin-regulated pathways." (PMID 36111327, 2022). "As an important insulin-sensitizing agent, metformin, which could relief insulin resistance and reduce the tumor-promoting effect of hyperinsulinemia, is widely used for diabetic patients." (PMID 35296101, 2022). "The precise mechanisms for postprandial hyperinsulinemia in horses are not fully understood but may involve alterations in pancreatic sensitivity to nutrients and incretins or reduced insulin clearance rates." (PMID 35978710, 2022). "Age-related hyperinsulinemia may be the consequence of an increase in insulin secretion and/or a decrease in its clearance." (PMID 36564463, 2022). "We hypothesized that in horses, exenatide would improve insulin sensitivity and reduce hyperinsulinemia." (PMID 35906619, 2022). "Despite being the most familiar way to provide insulin, subcutaneous insulin delivery is linked to needle pain, injection anxiety, lipodystrophy, compliance issues, and peripheral hyperinsulinemia; thus, there is a need for an insulin delivery system that is both less invasive and more biological." (PMID 36381916, 2022). "Thus, an antagonizing effect of leptin on hepatic insulin signalling was suggested under hyperinsulinemia conditions." (PMID 35896788, 2022). "When animals were exposed to 120‐min of hyperinsulinemia by euglycemic‐hyperinsulinemic clamps, there was a significant decrease in LV developed pressure, perhaps secondary to the systemic vasodilatory effects of insulin." (PMID 36073057, 2022). "There are several disease implications from our findings, chief among which is that vascular disorders arising from hyperinsulinemia may be perceived as not only an insulin signaling problem but one that also involves the TGF-β pathways." (PMID 35872017, 2022). "Second, Aβ degradation by an insulin-degrading enzyme (IDE) could be inhibited by GL-induced hyperinsulinemia." (PMID 35745215, 2022). "To clarify whether insulin contributes to microglial activation, we treated primary cultured microglia and BV2 cell lines with insulin in vitro to mimic hyperinsulinemia." (PMID 36466168, 2022). "Because the genetic alteration was elicited selectively in hepatocytes, the hyperinsulinemia noted in the Smo-KO mice may have been triggered by impaired insulin action in hepatocytes." (PMID 36535507, 2022). "The inhibition of endogenous insulin relies on the glucose-mediated feedback, and this might be prior to an exogenous hyperinsulinemia-mediated inhibition." (PMID 35935883, 2022). "Insulin injection or endogenous hyperinsulinemia is safe in long-duration diabetic patients." (PMID 35252207, 2022). "Studies have found that hypo- and hyperinsulinemia have little effect on total brain insulin, suggesting that brain insulin resistance may be due to decreased responsiveness to endogenous insulin." (PMID 35164216, 2022). "The present hyperinsulinemia could be attributed to the fact that insulin primarily increases the cellular uptake of glucose." (PMID 36248416, 2022).
Hyperinsulinemia (continued). "Invasive hemodynamics under these conditions revealed a significant difference in LV developed pressure between the saline and insulin groups at the end of euglycemic hyperinsulinemia (LV developed pressure—saline vs. insulin: 88.7 ± 0.1 vs. 79.4 ± 2.4, p < 0.05 by t‐test)." (PMID 36073057, 2022). "High-dose Aroclor exposure acutely increased random insulin concentration in media but decreased insulin concentration after a recovery period; this is in line with in vivo data showing initial hyperinsulinemia followed by hypoinsulinemia after a recovery period and Aroclor reexposure." (PMID 35156417, 2022). "A recent study concluded that genes affecting glucose metabolism, compensatory hyperinsulinemia from an insulin-resistant state, and hyperandrogenism may affect endometrial receptivity in PCOS women." (PMID 36359455, 2022). "Similarly, Phe stimulation was performed in the presence of 10 nmol/L insulin to model a condition that is comparable to postprandial hyperinsulinemia." (PMID 35436932, 2022). "A major observation of our work is that Insr mRNA was directly reduced by hyperinsulinemia in cultured cells, consistent with reports from other cell culture systems, and also is consistently negatively correlated with fasting insulin in both mouse and human skeletal muscle in vivo." (PMID 34921686, 2022). "The resulting systemic insulin insensitivity was compensated by hyperinsulinemia." (PMID 36003642, 2022). "Notably, while islets secreted almost no insulin in fasting conditions (27 pm ± 9 pm), they rapidly secreted insulin upon glucose challenge, reaching levels of 9.6 ± 4.2 nm after 4 h, resembling prediabetic hyperinsulinemia." (PMID 36285680, 2022). "Notably, IMQ treatment affected fasting insulin concentrations in a diet-dependent manner, with hyperinsulinemia observed in IMQ-HFD treated mice." (PMID 35874527, 2022). "It is indeed well established that A. muciniphila is negatively impacted by HFHS and that dietary factors, especially polyphenols, which favor the growth of the bacteria, lead to reduced inflammation, improved insulin sensitivity, and decreased hyperinsulinemia during OGTT in HFHS fed mice." (PMID 36052065, 2022). "The 2 nM hyperinsulinemia group had numerically less insulin‐stimulated glucose uptake." (PMID 34921686, 2022). "Hyperinsulinemia improvement could also be related to the enhanced insulin sensitivity, through the interruption of the compensatory response." (PMID 36233611, 2022). "Prolonged mitogenic signalling, such as chronic insulin exposure (hyperinsulinemia), has recently been shown to induce cell cycle re-entry in postmitotic cells, including hepatocytes, beta cells, neurons and adipocytes, with cell cycle re-entry in post-mitotic cells associated with cellular growth." (PMID 36483678, 2022). "Hyperinsulinemia indeed increases tau phosphorylation, favors the formation of senile plaques and inhibits degradation of extracellular neuronal Aβ by blocking the insulin-degrading enzyme." (PMID 35565839, 2022). "Insulin may also play homeostatic roles inenergy metabolism in the endometrium, with hyperinsulinemia contributing to poor implantation rates and increased miscarriage rates." (PMID 35565885, 2022). "The effects of central body fat on insulin sensitivity and the ovaries as a result of hyperinsulinemia may indirectly contribute to hyperandrogenemia." (PMID 35547420, 2022). "Higher post-load insulin response was a manifestation of hyperinsulinemia." (PMID 35090539, 2022). "First, hyperinsulinemia occurring during insulin therapy might induce sympathetic nervous system stimulation and consequently increase heart rate and QTc, which are well-known risk factors for ventricular arrhythmias." (PMID 36237914, 2022).
Hyperinsulinemia (continued). "The most important consequence of IR is the presence of a compensatory hyperinsulinemia state, characterized by an excessive and delayed rise in insulin secretion after meals, leading to triglyceride accumulation in hepatic and muscle tissues and a reduction of GLUT-4 translocation." (PMID 36615744, 2022). "Smoking is associated with decreased insulin secretion, HOMA-IR and hyperinsulinemia." (PMID 35929905, 2022). "Given the fact that offspring of obese dams exhibit hyperinsulinemia at P2142, insulin and IL-6 signaling might converge on FoxO1." (PMID 35896539, 2022). "Peripheral hyperinsulinemia leads to increased insulin secretion in the cerebrospinal fluid." (PMID 35989823, 2022). "Long-term increased insulin production results in pancreatic cell hypertrophy and hyperinsulinemia." (PMID 35563135, 2022). "During an insulin clamp, hyperinsulinemia is achieved by a constant insulin infusion." (PMID 35948530, 2022). "This can lead to hyperinsulinemia and an absolute increase in circulating insulin." (PMID 36501200, 2022). "Physical inactivity can potentially be related to increment IR, hyperinsulinemia, and its metabolic disorders via increasing inflammatory cytokines, reducing insulin sensitivity, inappropriate effect on body composition and weight gain, and insufficient effects on energy use in various body organs." (PMID 35578225, 2022). "This inconsistency is suggested to be caused by the duration and concentration of insulin treatment and the characteristics of the islet microenvironment, such as the glycemic levels, reflecting the dual role of insulin under the conditions of normal insulin signal and hyperinsulinemia." (PMID 35929791, 2022). "Interestingly, development of hyperinsulinemia was strongly sex-dependent, suggesting insulin levels to be a minor contributor to HFHSD-elicited brain dysfunction." (PMID 35111373, 2022). "In contrast, HFD-induced hyperinsulinemia was significantly reduced (fasting plasma insulin, 0.5 ± 0.07 ng/mL in MøFoxO1-KO versus 1.8 ± 0.35 ng/mL in HFD-fed WT littermates, P < 0.01), with a concomitant restoration of glucose-stimulated insulin secretion in MøFoxO1-KO mice." (PMID 35700043, 2022). "The reduction of hyperinsulinemia and associated hepatic SREBF1 activity observed herein, indicate that hepatic insulin signaling may be improved with 2′-FL, supported by the significant reduction of hepatic DAG." (PMID 35782914, 2022). "Hyperinsulinemia is a condition with extremely high levels of insulin in the blood." (PMID 35628058, 2022). "Chronic hyperinsulinemia may overstimulate and potentially trigger hyperactivation of downstream insulin effectors such as mTORC1." (PMID 36483678, 2022). "Finally, hyperinsulinemia can increase the viral load of SARS-CoV-2 since insulin raises the expression of ACE2 receptors located in the lung, cardiovascular system, pancreas, intestine, adipocytes, and immune cells, among others." (PMID 36312630, 2022). "The overstimulation of CB1 receptors might reinforce the insulin release which leads to permanent hyperinsulinemia." (PMID 36329422, 2022). "Minocycline also attenuated hyperinsulinemia and improved insulin sensitivity in HFD mice." (PMID 35784876, 2022). "Hypothesis: Acclimation to a high carbohydrate diet will result in improved insulin sensitivity and less marked postprandial hyperinsulinemia." (PMID 36214464, 2022). "In addition, a comparison of obese and non-obese hypertensive patients included in this study who had significantly different tissue sensitivity to insulin showed an equal effect of hyperinsulinemia on sodium handling." (PMID 36289636, 2022). "Thus some individuals in the general population, those with weight gain or hyperinsulinemia, and those who inject insulin, have plasma insulin concentrations at or above the EC50 insulin concentrations effective in gastric adenocarcinoma cells." (PMID 34554347, 2022).